SORL1 (sortilin related receptor 1)
Diseases named in the same sentence as SORL1 in open-access papers (continued):
Sharing a sentence is not in itself a finding about the gene and the disease.
ovarian carcinoma (continued). "Our findings suggest that the anti-SORL1 antibody and a small molecule inhibitor specific to FGFR4 both have the potential to overcome carboplatin resistance in ovarian cancer cells." (PMID 39858026, 2025). "SORL1 is unlikely to be the most important gene and definitely not the only gene that regulates tumor progression and chemoresponse in ovarian cancer." (PMID 39858026, 2025). "We further revealed that SORL1 interacts with EGFR and FGFR4, which may contribute to maintaining the levels of EGFR and FGFR4 proteins in ovarian cancer cells." (PMID 39858026, 2025). "Our findings also suggest that the interaction of SORL1 with EGFR and FGFR4 may play a role in increasing the levels of EGFR and FGFR4 proteins in ovarian cancer cells." (PMID 39858026, 2025). "This study also demonstrated the potential of targeting SORL1 with an antibody blocker or targeting FGFR4 with a small molecule inhibitor as new strategies to improve the response to chemotherapy in patients with recurrent and resistant ovarian cancer." (PMID 39858026, 2025). "Among these genes, we identified sortilin-related receptor 1 (SORL1) and its role in promoting carboplatin resistance through regulating the stability of epidermal growth factor receptor (EGFR) and fibroblast growth receptor 4 (FGFR4) using ovarian cancer models in vitro and in vivo." (PMID 39858026, 2025).
proteinopathies (1 paper, 2024). "Together, these co-pathologies suggest that SORL1 R953C may be mechanistically linked to multiple proteinopathies, clinically manifesting as AD but also impacting TDP-43 and α-synuclein histopathology." (PMID 38244079, 2024).
psychosis (1 paper, 2011). "Genetic variations at SORL1 may be associated with AD-related psychosis as well although this is still controversial." (PMID 22191060, 2011). "In addition, we reported correlations between SORL1 SNPs, psychosis, and proinflammatory cytokines." (PMID 22191060, 2011).
serous ovarian cancer (1 paper, 2025). "Moreover, we analyzed the SORL1 RNA expression and patient survival data using the TCGA high-grade serous ovarian cancer cases." (PMID 39858026, 2025).
uveitis (1 paper, 2025). An inflammatory process affecting a part of or the entire uvea. "To identify core regulatory genes shared between AS and uveitis, we first intersected genes from WGCNA-derived disease-associated modules and cross-disease DEGs, yielding five candidate genes: SORL1, TLR8, HLX, SLC25A20, and IGSF6." (PMID 40929101, 2025).
neurodegenerative disease (16 papers, 2012 to 2026). A disorder of the central nervous system characterized by gradual and progressive loss of neural tissue and neurologic function. "The replication of multiple SORL1 variants across neurodegenerative diseases and ancestrally diverse populations underscores its potential broad genetic contribution to neurodegeneration and reinforces its relevance across distinct clinical phenotypes." (PMID 41646738, 2026). "Based on the data from this study and previous reports, LRP10 expression and its association with neurodegenerative diseases demonstrate a high degree of overlap with SORL1, an established causative gene and risk factor in AD." (PMID 33913039, 2021). "It would therefore be of interest for future studies to determine SORL1-38b levels also for non-AD degenerative diseases, as well as looking further into the possible association between SORL1-38b and SNP24 that is specifically reported to associate with AD." (PMID 33726851, 2021). "In terms of neurodegenerative disease, recent work showing that VPS35 can associate directly with both soluble N-ethylmaleimide-sensitive factor attachment protein receptor (SNARE) proteins and the sortilin-related receptor SORL1 is thus particularly interesting." (PMID 22154191, 2012).
cancer (14 papers, 2012 to 2026). A tumor composed of atypical neoplastic, often pleomorphic cells that invade other tissues. "Overexpression of SPP1, a protein involved in ECM adhesion during wound healing, is also associated with cancer progression, metastasis, and apoptosis inhibition, just like an upregulation of the transmembrane sorting protein SORL1 that promotes cell proliferation in cancer cells." (PMID 33690729, 2021). "Under carboplatin treatment, compared to the control cells, the cancer cells with SORL1 knockdown contained a higher percentage of cells in the G2/M phase." (PMID 39858026, 2025). "We demonstrated the molecular mechanism by which SORL1 enhances cancer cell proliferation and platinum resistance through stabilizing the receptors of several growth factors." (PMID 39858026, 2025). "To develop effective approaches to target SORL1 in cancers, we will need to improve our knowledge of SORL1 functions in the context of specific cancer types." (PMID 39858026, 2025). "SORL1 coprecipitates with endosomal receptor HER2 in cancer cells and recycles it back to the plasma membrane, thus regulating its subcellular distribution." (PMID 37205232, 2023). "In addition to improving the methods of delivering the SORL1 antibody specifically to cancer cells, we also need to further evaluate the molecular, cellular, and in vivo effects of SORL1 inhibition." (PMID 39858026, 2025). "By comparing the effects of growth factor treatment on the control and SORL1 knockdown cell lines, we identified that SORL1 was involved in the cancer cell growth stimulated by CXCL12, BDNF, FGF1, and EGF1 in OVCAR8 cells and by BDNF, FGF1, and EGF1 in KRCH31 cells." (PMID 39858026, 2025). "However, to inhibit SORL1 in cancer cells more effectively and more specifically in a clinical setting, we still need to overcome several critical barriers." (PMID 39858026, 2025). "In tumors with high density of HER2 at the cell surface, the depletion of sortilin-related receptor 1 (SORLA) appears to direct HER2 to the degradative endolysosomal pathway and sensitizes cancer cells to lysosome targeting cationic amphiphilic drugs." (PMID 33348564, 2020). "Here, we find that sortilin-related receptor 1 (SORLA; SORL1) co-precipitates with HER2 in cancer cells and regulates HER2 subcellular distribution by promoting recycling of the endosomal receptor back to the plasma membrane." (PMID 31138794, 2019). "The role of SORL1 in human cancer has not been extensively studied." (PMID 39858026, 2025).
tumor (14 papers, 2012 to 2025). "Compared to the control tumors, the SORL1 knockdown tumor tissues showed significant discoloration and loss of cellular details." (PMID 39858026, 2025). "In particular, our results point to the scenario where high SORL1 expression occurs in tumor-supportive GAMs, while low SORL1 expression is associated with pro-inflammatory phenotypes of microglia/macrophages." (PMID 38499808, 2024). "Widespread gaps were readily apparent in the SORL1 knockdown tumor tissues, which indicates the presence of fluid and exudative material within the tumors." (PMID 39858026, 2025). "We found that SORL1 expression is significantly higher in the tumor samples compared to the normal ovary samples." (PMID 39858026, 2025). "Through H&E staining of the tumor tissue sections, we identified that tumors with SORL1 knockdown showed increased amounts of necrosis in comparison to the control tumors." (PMID 39858026, 2025). "To further characterize the potential functional interactions between various cell types present in the tumor microenvironment in the context of SORL1 levels in GAMs, we implemented the CellChat analysis." (PMID 38499808, 2024). "Among “high-SORL1” clusters, cluster 7 was characterized by the expression of immediate early genes, SPP1, a gene associated with tumor-promoting GAMs, and ID2 involved in pro-tumorigenic polarization of myeloid cells." (PMID 38499808, 2024). "We further identified that an anti-SORL1 antibody inhibited the pro-tumor functions of SORL1." (PMID 39858026, 2025). "In turn, high-SORL1 GAMs sent pro-tumorigenic signals to the tumor cells." (PMID 38499808, 2024). "To clarify the survival mechanism related to the relationship between BLCA and the expression of SORL1, we explored the differences in tumour-infiltrating immune cells between patients with high and low SORL1 expression (the group allocation of patients was the same as the previous step)." (PMID 34976002, 2021). "ONECUT1, ADAMTS, IFNAR2, MSR1, and SORL1 affect migration or metastasis, a process that involves attachment of tumor cells to the basement membrane, degradation of local connective tissue, and penetration and migration of tumor cells through stroma." (PMID 23151184, 2012). "Therefore, the upregulation of SORL1 expression inhibited the expression of PD-1/PD-L1 and then reduced the state of immune suppression, reactivating immune cells and allowing them to attack tumor cells." (PMID 34976002, 2021). "When we collected the tumors and examined the levels of protein expression, we found that SORL1 knockdown led to the downregulation of both EGFR and FGFR4 in the tumor samples." (PMID 39858026, 2025). "When we knocked down SORL1 expression in the KRCH31 cells by stably expressing SORL1-targeting shRNA, tumor growth was significantly suppressed in comparison to the tumors formed by the control KRCH31 cells." (PMID 39858026, 2025). "Intriguingly, CAFap presented significantly more interactions with tumor-infiltrating T-cell clusters than CAFmyo (p = 0.002), with a similar interactive pattern as that of TAM (e.g., LGALS9_HAVCR2/SORL1/CD47)." (PMID 36333338, 2022). "Other ligand-receptor pairs revealed by this analysis included TNF-TNFRSF1A sent by medium-SORL1 expressing GAMs, TNFSF12-TNFRSF12A (high-SORL1 GAMs to tumor cells), PDGFB-PDGFRA (medium- and high-SORL1 GAMs to several populations), and THY1-(ITGAM + ITGB2) received by high-SORL1 GAMs (Fig. EV2B)." (PMID 38499808, 2024). "Patients #5, #6, and #7 (without tumor samples) showed an overlap of four genes (SORL1, PTPRC, MIR6819, and NAMPT), while #6 and #7 also shared five genes (CELF2, EDEM3, SMCHD1, RAVER1, and CXCR1)." (PMID 39001407, 2024). "SORL1, as a protective factor, may alleviate the state of immune suppression and inhibit the M2 macrophage-induced EMT phenotype of tumour cells." (PMID 34976002, 2021). "SORL1 might reduce immune suppression and inhibit the M2 macrophage-induced EMT phenotype of tumor cells." (PMID 34976002, 2021).
neurological disease (3 papers, 2020 to 2024). "It is unknown whether her 3-year course of spasticity is related to the SORL1 variant or is an unrelated case of a neurologic disease." (PMID 38244079, 2024). "For example, as the second-ranked miRNA, Hsa-miR-1229 directly regulated the expression level of AD-related gene SORL1, and other targeted genes, which could be involved in the biological processes of nervous system development and neurological disease." (PMID 32154224, 2020).
cardiovascular disease (2 papers, 2016 to 2025). "This biological and neuroimaging evidence may suggest that SORL1 rs3824968 is associated with brain morphology in terms of A allele-related volumetric reduction caused by high Aβ load, cardiovascular disease, or both." (PMID 26996954, 2016).
SORL1 also shares sentences with these, for which no sentence is quoted: atherosclerosis (5 papers); Depression (4); frontotemporal dementia (4); amyotrophic lateral sclerosis (2); bladder (2); brain disease (2); breast tumors (2); colorectal cancer (2); coronary artery disease (2); glioblastoma (2); Hypertension (2); infection (2); primary progressive aphasia (2); type 2 diabetes (2); acrodysostosis (1); acute lymphoblastic leukemia (1); aortic stenosis (1); Apathy (1); bipolar disorder (1); brain tumors (1); cervical squamous cell carcinoma (1); chronic myeloid leukemia (1); colon cancer (1); corticobasal syndrome (1); dengue (1); diarrheal disease (1); endocervical adenocarcinoma (1); esophageal cancer (1); familial hypercholesterolemia (1); gastric cancer (1).
A further 28 diseases each share a sentence with SORL1 in 1 paper.